IRF1 (interferon regulatory factor 1)
Diseases named in the same sentence as IRF1 in open-access papers (continued):
Sharing a sentence is not in itself a finding about the gene and the disease.
viral infection (continued). "IRF1 can be induced by viral infection, dsRNA, IFNα/β or other cellular factors, and participates in antiviral and antibacterial responses, in hematopoietic differentiation and cytokine recognition." (PMID 32983049, 2020). "IFN-regulatory factor gene family encodes multiple transcription factors including IRF1, IRF3 and IRF7, and plays essential roles in host defense against viral infection through regulation of IFN expression." (PMID 32983049, 2020). "As a member of IRF transcription factor family that regulates IFN expression during viral infection, IRF1 plays a very important role in regulating the expression of IFNs and ISGs, in addition to NF-κB, IRF3, and IRF7." (PMID 32983049, 2020). "All these factors are constitutively expressed and are activated upon viral infection except for IRF1, which is induced upon IFN signaling." (PMID 31319869, 2019). "In conclusion, our study highlights a critical role for IRF1 in regulating constitutive antiviral gene networks to confer resistance against viral infections in human respiratory epithelial cells." (PMID 31156620, 2019). "Phosphorylated STAT3 can inhibit IRF1 transcriptional activation and thus represses the induction of IFNs upon viral infection." (PMID 30735121, 2019). "The result demonstrated that the protein level of the endogenous fe-IRF1 was reduced by viral infection in a viral dose-dependent manner." (PMID 30009167, 2018). "Other members of the network also reappeared in the gene set enrichment analysis as members of pathways associated with viral infections (DDX58, IFIT1, IRF1, MX1, STAT1) or viral carcinogenesis and cell cycle (CCND1, CCND3, CCNE1, CDC20, E2F2, RANBP1)." (PMID 30042828, 2018). "IRF1 mRNA rises in response to IFNs, double-stranded RNA (dsRNA), cytokines, some hormones, and viral infection and then promotes the expression of antiviral proteins and restricts the replication of many viruses." (PMID 30009167, 2018). "The activation of TFs including NF-κB, AP1, IRF3 and IRF1, induced by viral infection, coordinately and cooperatively trigger IFNβ or IFNλ1 induction." (PMID 29020068, 2017). "Whereas IRF-7 is activated in response to viral infections and NF-κB, IRF-1 responses are mainly triggered by IFN-γ, although they can also be activated by cytosolic pattern recognition receptors." (PMID 28122985, 2017). "MAVS associated with mitochondria has the ability to induce both type I and III IFNs, while MAVS associated with peroxisomes selectively induces type III IFN production following viral infection in an IRF-1 dependent fashion." (PMID 28000722, 2016). "The cellular transcription factor IRF-1 impacts various physiological functions, including the immune response to viral infection." (PMID 27795392, 2016). "Interferon regulatory factor 1 (IRF1), as an important transcription factor, is abundantly induced upon virus infections and participates in host antiviral immune responses." (PMID 26593937, 2015). "Although many studies have already focused on antiviral functions of human, mouse or fish IRF1, the role of poIRF1 in controlling porcine viral infections is poorly understood." (PMID 26593937, 2015). "Comparative transcriptome analysis of virus infected wild type and IRF1−/− cells is planned to identify these antiviral effectors preferentially induced by IRF1 that inhibit viral infections in a virus-type specific manner." (PMID 26593937, 2015). "Subsequently, analysis of IRF1−/− cells from mice has shed light on the unnecessary role of IRF1 in IFN-β induction by virus infection." (PMID 26593937, 2015). "As the first member of IRF family, IRF1 is constitutively expressed in most cell types and is dramatically induced upon viral infection, treatment with dsRNA or IFN stimulation." (PMID 26593937, 2015).
viral infection (continued). "It has been suggested that IRF-1 is one of the principal host regulatory factors involved in cellular responses to combat viral infection via apoptosis and in the clearance of viruses from apoptotic cells via PSR induction." (PMID 25342322, 2014). "To investigate the relationship between PSR and IRF-1 during viral infection, we wanted to investigate the structure of the PSR promoter." (PMID 25342322, 2014). "In this study, we determined that interferon regulatory factor-1 (IRF-1) was dramatically upregulated upon viral infection in the fish cell." (PMID 25342322, 2014). "This is the first report to show the potential role of IRF-1 in triggering the induction of apoptotic cell clearance-related genes during viral infection and demonstrates the extensive crosstalk between the apoptotic and innate immune response pathways." (PMID 25342322, 2014). "IRF-1 expression is considerably upregulated during viral infections and stimulations by the interferon family." (PMID 24066008, 2013). "As IRF1 is a short-lived protein, rapid changes in steady-state levels occur in response to stimuli such as DNA damage or viral infection." (PMID 22295238, 2011). "Genetic profiling studies are planned with wild type and IRF-1-/- cells to identify novel gene signatures that can help define antiviral effector and immunomodulatory genes that inhibit viral infections and shape adaptive T cell responses." (PMID 21909274, 2011). "Moreover, our findings align with studies showing that IRF3 can still be induced after viral infection even when IRF1 is knocked down, suggesting their independent activation." (PMID 40643511, 2025). "In addition to its induction by viral infections, basal expression of IRF1 has been shown to drive the optimal expression of a battery of antiviral effector genes that defend against various pathogenic RNA viruses." (PMID 40586041, 2025). "IRF-1 plays a crucial role in the regulation of immune response, viral infection, and inflammation." (PMID 39532800, 2024). "Also, a transcriptome study of neuron cultures after viral infection detected upregulation of Ccl4, Cxcl10, Oas1, Irf1, and Irf7, an important modulator of the type I interferon process." (PMID 38189117, 2024). "IRF1 expression is robustly induced in epithelial cells in response to IFNβ, and IRF1-deficient mice are more susceptible to viral infections." (PMID 37065193, 2023). "The contrast between AR STAT1 and IRF1 deficiencies is striking in this respect, as the two patients with IRF1 deficiency did not suffer from the life-threatening viral diseases seen in patients with AR complete STAT1 deficiency." (PMID 36736301, 2023). "Avian IRF1 plays an important role in host innate immunity against viral infection." (PMID 37256135, 2023). "TRIM21 promotes IRF1 protein synthesis by inhibiting PKR activation upon viral infection." (PMID 37327222, 2023). "Interestingly, SOX10 has been associated with the regulation of immune-related pathways, including IRF1, a well-characterized regulator of viral infection." (PMID 38201278, 2023). "Given that TRIM21 suppresses PKR activation, we investigated whether TRIM21 can resist viral infection by promoting the protein synthesis of IRF1." (PMID 37327222, 2023). "Therefore, in addition to inducing IRF1 transcription during viral infection, we have outlined an alternative pathway to enhance IRF1-dependent antiviral immunity." (PMID 35972291, 2022). "IRF1 may play a more dominant role in regulation of host antiviral response in the scenario when type I IFN signaling is suppressed during a viral infection." (PMID 35891486, 2022). "IRF1 may play an important role in the host to defend against the viral infection, which needs to be further explored." (PMID 35159296, 2022). "We show that in the absence of IRF1, cells exiting the naive pluripotent stem cell state are more susceptible to viral infection." (PMID 35852463, 2022).
viral infection (continued). "Moreover, IRF1 target genes robustly and rapidly respond to viral infection, which is essential for host defense at the early stage." (PMID 35972291, 2022). "Furthermore, deletion of the EpiLC‐specific enhancer controlling Irf1 expression also increased viral infection compared with WT cells." (PMID 35852463, 2022). "IRF-1 is only expressed at very low levels in most cell types, however higher expression levels are observed in immune cells, and it is strongly induced by virus infection, IFN-α, and IFN-γ in other cells." (PMID 33807175, 2021). "Our study identifies a novel mechanism for IRF1 induction in response to viral infection of human macrophages that could be relevant not only to defense against HMPV, but also to other viral, bacterial and fungal pathogens." (PMID 34248923, 2021). "In contrast to non-cytopathic virus infection, our study suggests that the CNS innate response mechanism has a relatively higher-level synergy between MDA5, IRF1, CCL5, TNF-α, and IFN-γ to compensate for the IFN-I signaling loss to deal with a cytopathic virus infection." (PMID 32575459, 2020). "The enhancement of reprogramming by virus infection might be partially due to the activation of JAK-STAT downstream of IRF-1 during reprogramming, which might enrich the mechanism of enhancement by retrovirus mediated gene overexpression during reprogramming." (PMID 33246502, 2020). "It is well established that IRF-1 is involved in the response to viral infections." (PMID 33246502, 2020). "Interestingly, IL-33 and sST2 transcript correlated with IRF-1 mRNA levels, which was found to be essential for IL-33 production under viral infections in endothelial cells." (PMID 33133101, 2020). "Another study indicated that Mtb is able to induce the production of TNF-α and IL-1β in RAW264.7 cells and that it activates the NF-κB pathway through TLR2-mediated signaling, thereby contributing to the induction of IRF-1, one of the most potent ISGs against viral infection." (PMID 30717477, 2019). "In addition to IRF3, other IRFs have been involved in the amplification of type I IFN response following viral infection: IRF7 plays an instrumental role whereas IRF1 and IRF5, are reported to be dispensable for inducing type I IFN." (PMID 31319869, 2019). "IRF1 can be induced by viral infection to eliminate viral infection." (PMID 30009167, 2018). "It is known that the IRF-1 levels rapidly increase in response to stimuli such as viral infection, DNA damage, or TLR stimulation due not only to its transcriptional activation but also to changes in its posttranslational modification that greatly increase the protein stability." (PMID 29545793, 2018). "When induced by various stimuli, such as viral infection and interferon, IRF1 acts as a transcriptional activator of specific IFN-stimulated genes that mediate diverse functions including cellular responses to inflammation, programmed cell death and tumor suppression." (PMID 26362401, 2015). "Taken together, IRF-1 potentially may play a key role in linking the immune response and apoptosis during viral infection, and the coexistence of phagocytic cells with virus-infected apoptotic cells could affect the extent of viral assembly." (PMID 25342322, 2014). "However, little is known about the mechanism by which IRF-1 activates the promoter of PSR upon viral infection." (PMID 25342322, 2014). "Simultaneously, we also found that IRF-1 increased constitutively during viral infection." (PMID 25342322, 2014). "Although both, type I IFN and IRF-1 mediate their antiviral action by inducing overlapping subsets of IFN stimulated genes, the functional role of this alternative antiviral action of IRF-1 in context of viral infections in vivo remains unknown." (PMID 24675692, 2014). "In conclusion, antiviral response of IRF-1 was crucial for survival of viral infection." (PMID 24675692, 2014).
viral infection (continued). "In particular, expression of IRF1 was shown to drive the expression of many ISGs and confer resistance to various viruses, thus demonstrating a key role in host resistance to viral infections." (PMID 24098125, 2013). "IRF1 mRNA is dramatically upregulated upon viral infection or IFN stimulation." (PMID 22295238, 2011). "Mutations affecting IRF family members IRF1, IRF3, IRF7, IRF8, or IRF9 have been described in patients presenting with inborn errors of immunity (IEI) highlighting the importance of these factors for the cellular host defense against mycobacterial and/or viral infections." (PMID 37809068, 2023). "Therefore, we speculated that induction of the transcription factor IRF1 determined the elevated XAF1 expression during viral infection." (PMID 35972291, 2022). "Thus, the association of IRF-1, IFI-44, Mx1, OAS2, and HSH2D with HLA-DR could suggest a possible relationship between viral infection and HLA-DR expression." (PMID 30374345, 2018). "It is unknown whether IRF-1 plays a role in PSR induction during the viral infection." (PMID 25342322, 2014). "Furthermore, virus infection leads to the activation of NF-κB and IRF1." (PMID 22363706, 2012). "The transcription factor IRF1 contributes to both IFN-α/β and IFN-γ signaling to regulate viral infection." (PMID 39817192, 2025). "Studies in HeLa cells in the context of viral infection suggested that the promoter region of CARINH has potential enhancer activity, boosting the expression of IRF1 independently of CARINH expression levels." (PMID 39773901, 2025). "Its signaling pathway activates interferon regulatory factor 1 (IRF1) and other interferon-stimulated genes, including ZBP1, thereby promoting PANoptosis, especially in the context of viral infections." (PMID 39591329, 2024). "IRF1 and IRF3 upregulate transcription of certain ISGs in IFN-independent manners during virus infection." (PMID 37197656, 2023). "Amongst the genes with the most significant difference in expression between the WT and mutant virus infections were antiviral genes (e.g., IRF1, IFIT2, OASL) that exhibited a higher expression in the WT virus infection." (PMID 37243147, 2023). "Avian interferon regulatory factors 1 and 7 (IRF1 and IRF7) play important roles in the host’s innate immunity against viral infection." (PMID 35891486, 2022). "As expected, HSV-1 infection induced a substantial increase in IRF-1, TNF-α, and IL-15 mRNA levels in the wild-type Vero cell line, increasing IRF-1 up to 30-fold 2 days after viral infection." (PMID 35897807, 2022). "It has been reported that interferon can significantly trigger the production of many interferon-induced genes (IFIT1, IFITM3, MX-1, OASL, ISG15, PKR, GBP1, Viperin, BST2, IRF-1, and CXCL10), which play key roles in the resistance to viral infection." (PMID 36337195, 2022). "Both IRF-1 and type III interferons can induce the interferon-stimulated response (ISR), a robust cellular response important for virus infection control." (PMID 35095855, 2021). "We demonstrate that activation of type III IFN induction by virus infection is inhibited by human and animal RV NSP1s, and reveal a previously undescribed role for NSP1 as an inhibitor of IRF-1." (PMID 33807175, 2021). "IL-33 and sST2 mRNA levels correlated with IRF1, an IFN induced factor relevant in responses to viral infections and interferon mediated proinflammatory responses highly represented in duodenal tissues in ACD." (PMID 33133101, 2020). "Therefore, it is possible that virus infection could induce the expression of IRF-1." (PMID 33246502, 2020). "Collectively, these results disclosed that EV71 infection predominantly induces type III IFN expression through the TLR3/IRF1/type III IFN regulatory axis in the immunopathogenesis and antiviral response to the viral infection in mouse intestine." (PMID 33203755, 2020).
viral infection (continued). "In response to viral infection, among the IRF family members, particularly IRF-1, IRF-3, and IRF-7 are necessary for the production of type I IFN and also IFN-inducible genes (Bego, Mercier & Cohen, 2012)." (PMID 32566414, 2020). "IRF1, one of the IRF family of transcription factors, responds to viral infection and exerts antiviral activity in the early stages of viral infection in the respiratory tract." (PMID 33203755, 2020). "Taken together, our selective knockdown of this small subset of the ~300 DEGs demonstrates that IRF1 maintains constitutive expression of antiviral genes, which is one of the many mechanisms by which respiratory epithelial cells may be protected from viral infection." (PMID 31156620, 2019). "IRF1 further regulates RSAD2 (> 2258.2-fold change, FDR p-value 5.2 × 10− 25), which has been reported to be highly expressed during viral infections." (PMID 30621583, 2019). "Cells displayed a marked upregulation of many genes known to be involved in the mammalian response to viral infection, including viperin, Mx1, IRF7, IRF1, and RIG-I with approximately 10% of the genes being uncharacterized transcripts." (PMID 29213275, 2017). "A number of ISG can also be induced by viral infections in an IFN-independent manner, for example via interferon regulatory factor 1 (IRF1)." (PMID 27827855, 2016). "IRF1 and IRF2 of the IRF family of transcription factors play distinct roles in cellular response to viral infection." (PMID 25960866, 2015). "The different roles of IRF1 in the early and late phases of Type I IFN responses in response to viral infections also require further explorations." (PMID 26593937, 2015). "Compared to normal viral infection, we found that PSR expression was delayed, viral replication was increased and virus-induced apoptosis was inhibited following IRF-1 suppression with morpholino oligonucleotides." (PMID 25342322, 2014). "The upstream molecular mechanisms resulting in the activation of IRF-1 and IRF-7 during viral infection have begun to be elucidated in recent years." (PMID 19404407, 2009). "CARINH and IRF1 are coordinately increased in the circulation of patients infected with human metapneumovirus, influenza A virus, or SARS-CoV-2, and in macrophages in response to viral infection or TLR3 agonist treatment." (PMID 39773901, 2025). "Besides, compared all other T-cell subtypes, the CD38+HLA-DR+ T cells exhibited higher expression levels of interferon regulatory factors (IRF1 and IRF7) and T cell factor -7 (TCF7), indicating the host’s immune response against viral infection." (PMID 40370439, 2025). "Additionally, DEGs related to the response to viral infections, such as DDIT4, CXCR4, EIF5A, TNFAIP3, BCL2, and IRF1, were also upregulated in NBs." (PMID 38440735, 2024). "We were surprised to see the dramatic inhibition of BRD4i pSer2 Pol II binding, since IRF1 is engaged with pSer2 Pol II in the absence of viral infection, and pSer2 Pol II binding to intrinsic IIR genes is IRF1-dependent." (PMID 38601157, 2024). "IRF-1, the first member of the IFN regulatory factor family, exerts effects in various physiological and pathological contexts including inflammatory injury, viral infection, development of the immune system, and autoimmunity." (PMID 35756539, 2022). "IRF1 also plays a positive regulatory role in the innate immune response to viral infection by enhancing the phosphorylation of IRF3 and the production of types I and III IFN triggered by viral infection." (PMID 35379320, 2022). "However, IRF-1 expression levels were ~two-fold lower in GR1−/− and G+/−GR1−/− cell lines after viral infection." (PMID 35897807, 2022). "We hypothesized that upon genotoxic insult, IRF1 might be a downstream target of the RLR/IRF3 pathway, as reported for virus infection, and thereby link RLR activity to the DNA damage response." (PMID 35436994, 2022).